IL6 (interleukin 6)
Diseases named in the same sentence as IL6 in open-access papers (continued):
Sharing a sentence is not in itself a finding about the gene and the disease.
COVID-19 (continued). "Despite the small number of such case during our study, it nevertheless highlights the importance of IL-6 and IL-10 as COVID-19 disease severity predictors." (PMID 32475230, 2020). "The high levels of IL-6 observed in COVID-19 patients is likely a driver of this NETosis, as in other inflammatory diseases IL-6 induces the systemic release of NETs." (PMID 33101306, 2020). "In patients with COVID-19, disease progression is significantly associated with older age and higher circulating levels of CRP, procalcitionin, IL-6, and lactate." (PMID 33239109, 2020). "There is an ongoing prospective, randomized, interventional trial comparing the therapeutic effects of individual and simultaneous blockade of IL-6 and IL-1 versus standard care in COVID-19 patients." (PMID 33041830, 2020). "It therefore appears that tocilizumab can be used to effectively treat patients with COVID-19, and that its beneficial effects are related to its ability to suppress IL-6-related febrile and inflammatory storm responses." (PMID 33031060, 2020). "We show here a short kinetic of IL-6 serum concentration in the first 24 COVID-19 patients treated with itolizumab." (PMID 33292350, 2020). "Thus, in this study, we aimed to determine whether IL-6 levels are associated with disease severity and mortality in COVID-19 patients and investigate whether dynamic changes in IL-6 levels are predictive of pulmonary lesions caused by ARDS in hospitalized COVID-19 patients." (PMID 32765283, 2020). "This massive cytokine boost promotes high levels of interleukin-6 (IL-6) production, increased levels of clotting factors and fibrinogen leading to significantly higher rates of thrombosis in COVID-19 patients." (PMID 32899231, 2020). "With this in mind, here we discuss the potential pathogenetic mechanisms and therapeutic options for COVID-19, focusing on IL-6-signal transducer and activator of transcription 3 (STAT3) signaling." (PMID 33014208, 2020). "For instance, in a series of 99 COVID-19 cases from hospitals in Wuhan and Shanghai, China, half of the patients show elevated IL-6 levels." (PMID 33178109, 2020). "Neutralization of IL-6 signaling using anti-IL-6 receptor antibodies (tocilizumab and sarilumab) or anti-IL-6 antibodies (clazakizumab) have been tested in patients with COVID-19 showing hyper-inflammation." (PMID 33634100, 2020). "The D-dimer level positively correlated with IL-6 (R = 0.5) at baseline when the COVID-19-infected patients were admitted." (PMID 33195321, 2020). "While the elevation of CXCL10, IL-10, CCL2, IL-6 has been extensively documented in severe COVID-19, our work demonstrates a clear correlation between these cytokines and plasma viral load." (PMID 33317616, 2020). "The levels of TNF-α and IL-6 in the peripheral blood were significantly increased in COVID-19 patients, the degree of this elevation was significantly correlated with the severity of disease." (PMID 32976531, 2020). "Because elevated levels of IL-6 have been associated to poor prognosis and predictor of mortality, the use of IL6 antagonists has been early proposed for the COVID-19 treatment." (PMID 33195215, 2020). "TLR4, CD40, IL-6, IL-8, TNF, IFN-α, ICAM1, and CXCL12, which are associated with NF-kB pathways, and TRAF protein family members were upregulated in the lungs of COVID-19 patients." (PMID 33584667, 2020). "As of November 2020, there exists no consensus across international guidelines on the treatment of COVID-19 patients with anti-IL-6 monoclonal antibodies (mAbs)." (PMID 33510644, 2020). "IL-6 is a cytokineassociated with disease severity in COVID-19 patients, and for which clinical trials targetingthe IL-6 receptor with tocilizumab are underway." (PMID 32702726, 2020). "Such cocktails are intended to tackle the release of pro-inflammatory cytokines IL-1β and IL-6 mediating lung and tissue inflammation, fever, and fibrosis, as they are supposed to be responsible for the emergence of COVID-19." (PMID 33692684, 2020).
COVID-19 (continued). "It is likely that in the massively inflamed lung of COVID-19, selective inhibition of IL-6 blocks but one of many mediators with redundant pro-inflammatory functions." (PMID 33442386, 2020). "Our results showed significant increases in IL-6 and IL-10 in the peripheral blood of patients with severe cases of COVID-19 compared to the levels in patients with mild cases." (PMID 32669467, 2020). "IL-6 plays a central role in the cytokine storm, and tocilizumab has already been used as a biological with anti-IL-6 effects in COVID-19." (PMID 32915172, 2020). "IL-6 is the predominant cytokine observed in COVID-19 adult cases and is significantly correlated with ICU admission." (PMID 32903279, 2020). "In patients affected by COVID-19, most of the severe cases demonstrated massive systemic levels of infection-related biomarkers and inflammatory cytokines, namely serum IL-6, tumour necrosis factor-α (TNFα) and ftn." (PMID 32664543, 2020). "Awareness of IL-6’s potential role in COVID-19 immunopathogenesis prompted new clinical trials aimed at assessing TCZ efficacy in COVID-19." (PMID 32636755, 2020). "Sharp and dramatic increase in circulating levels of these pro-inflammatory cytokines can be defined as a cytokine storm, which is mainly through IL-6 in COVID-19 patients." (PMID 33352869, 2020). "This phenomenon is also the main reason why although the number of CD4+ Th cells in the peripheral blood significantly decreased, the plasma levels of TNF-α and IL-6 significantly increased in patients with COVID-19." (PMID 32976531, 2020). "Other monoclonal antibodies specifically targeting IL-6 pathways, such as sarilumab and siltuximab, are also recommended for COVID-19 treatment." (PMID 33269102, 2020). "The results from this work show that one dose of itolizumab reduced the baseline serum levels of IL-6 in critically and severely ill COVID-19 patients as well as stabilized the baseline low levels in moderately ill elderly COVID-19 patients." (PMID 33292350, 2020). "While a major driver of the cytokine storm in COVID-19 patients, IL-6 has both pro- and anti-inflammatory properties, giving it a complex role in COVID-19 pathology." (PMID 33101306, 2020). "The risk associated with male sex raises a topic of great interest: the effects of estrogens on IL-6 and on COVID-19 progression." (PMID 32983180, 2020). "Collectively, these results suggest that humoral immune responses are associated with the inflammatory factors IL-6, CXCL10, and C5a in COVID-19 patients." (PMID 32963357, 2020). "By combining the core target gene bar chart and the KEGG relationship network diagram, we can see that IL6 is one of the most critical genes for anti-inflammatory and immune regulation in COVID-19 patients treated with DYY." (PMID 32536965, 2020). "In particular, we found that serum levels of IL-6 and IL-8 were significantly higher in COVID-19 patients as compared with heath donors with the AUC, which represents the combination of detecting sensitivity and specificity, at 0.84 and 0.98, respectively." (PMID 33488599, 2020). "Inflammatory markers are closely related to severity in COVID-19 pathology and selective blockade of IL-6 has been demonstrated to be a good therapeutic strategy in COVID-19 pathology." (PMID 33072099, 2020). "COVID-19 severity is associated with the levels of CEA, IL-6, CRP, PCT, Fer, D-dimer, L%, Neu%, and WBC." (PMID 33537326, 2020). "Ex vivo analysis revealed significantly elevated BTK activity, as evidenced by autophosphorylation, and increased IL-6 production in blood monocytes from patients with severe COVID-19 compared with blood monocytes from healthy volunteers." (PMID 32503877, 2020). "Since the key cytokine in this hyper-inflammatory response is IL-6, it seems imperative to test the efficacy of IL-6 blockers such as tocilizumab in treating critical COVID-19 patients." (PMID 33178522, 2020).
COVID-19 (continued). "Monoclonal antibody-based rheumatoid arthritis drug tocilizumab which is also an inhibitor of IL-6 receptor found to be effective in critically ill COVID-19 patients with cytokine storms and elevated IL-6 levels." (PMID 32973505, 2020). "Although the exact mechanism of TTS in COVID-19 is not fully explained, a cytokine storm syndrome-like picture has been seen in COVID-19 patients, with a high burden of pro-inflammatory cytokines like IL-6, which was reported in 2 cases." (PMID 33043251, 2020). "Most patients with severe COVID-19 show significantly elevated serum levels of inflammatory cytokines, such as IL-6 and IL-1, as well as IL-2, IL-17, G-GSF, GM-GSF, IP-10, MCP1, MIP-1a (also known as CCL3), and TNF, known as a cytokine storm." (PMID 32983180, 2020). "We performed log-linear regression analysis between the case fatality rate of COVID-19 and allele frequencies of the polymorphisms of the IFITM3, ACE2, TMPRSS2, and IL6 genes in several ethnic groups." (PMID 33396837, 2020). "Contemporaneous increase in ferritin, IL-6 and ALT levels associated with decreased albumin concentration suggest more significant liver involvement in the course of COVID-19." (PMID 32403255, 2020). "TCZ is therapeutically applied in rheumatoid arthritis, but Chinese government have stated that it can be prescribed for COVID-19 patients with severe lung damage and high IL-6." (PMID 33195318, 2020). "For the first time, it is reported that this antibody is able to decrease circulating IL-6 levels in patients with critical and severe COVID-19." (PMID 33292350, 2020). "It has been demonstrated that increased levels of pro-inflammatory cytokines, including interleukin 1β, interleukin 6 (IL-6), and tumor necrosis factor alpha (TNFα), in patients with COVID-19 can induce upregulation of procoagulants." (PMID 33118741, 2020). "TCZ, a first-line drug in specific pathologies, proved to be effective and particularly safe for acute treatment as would required for blocking IL-6 in COVID-19." (PMID 32636755, 2020). "COVID-19 in the lungs activates various leukocytes to release a cascade of cytokines, including interleukin-6 (IL-6)." (PMID 33352638, 2020). "Patients with severe COVID-19 also presented lymphopenia, elevated interleukin-6, procalcitonin, and D-dimer." (PMID 33167876, 2020). "There are currently multiple clinical trials attempting to elucidate the role of anti-IL6 therapies to attenuate ARDS in COVID-19 (clinicaltrials.gov: NCT 00531856; NCT04363853; NCT04335071)." (PMID 33537342, 2020). "Multiple trials are therefore looking at the effects of Tocilizumab, an IL-6 receptor antibody that inhibits IL-6 activity, on treatment of COVID-19, with promising findings." (PMID 33469465, 2020). "For the prediction of COVID-19 patient’s disease status, we analyzed IL-6 and IL-8 levels among healthy people, mild, and severe COVID-19 patients." (PMID 33488599, 2020). "Elevated plasma levels of pro-inflammatory cytokines are observed in COVID-19 infected patients; in particular, IL-6 and ferritin release have been identified as predictors of fatality." (PMID 32574257, 2020). "Intriguingly, severe COVID-19 patients show elevated levels of serum cytokines such as IL-6, TNF-α, and IL-10, and also increased sCD25 in the serum." (PMID 33178221, 2020). "In severe COVID-19 cases, the macrophage-epithelial interaction promotes a further augmentation of IL-6 (and IL-2R, IL-10, and TNFα), whereas CD4+ (including IFNγ-expressing CD4+ T cells) and CD8+ T-cells markedly decrease in number." (PMID 32517353, 2020). "Laboratory values for LDH, CRP, and IL-6 were significantly higher in the group of COVID-19-positive patients who developed ARDS compared to COVID-19 patients with mild clinical course." (PMID 33123171, 2020). "Compared to healthy people, both IL-8 and IL-6 levels in the sera of COVID-19 patients were significant higher." (PMID 33488599, 2020).
COVID-19 (continued). "A systematic review of the clinical data of IL-6 inhibitor tocilizumab (TCZ) for severe COVID-19 points towards efficacy in reducing mortality from the disease." (PMID 33194450, 2020). "Consistent with previous reports, the serum IL-6 concentrations in the severe COVID-19 patients examined in this study were relatively lower than those in patients with severe ARDS." (PMID 32826331, 2020). "We define the initiation phase of the lethal immunopathology in fatal COVID-19 patients as the first 4 days after disease onset, when IL-6 levels first begin to increase, and the amplification phase can be avoided by timely interventions." (PMID 32766256, 2020). "Ingenuity Pathway Analysis (IPA) showed that IL6 and IL6R appeared to be implicated in several pathogenetic mechanisms associated with COVID-19 severity and mortality as well as with neurodegenerative diseases mediated by neuroinflammation." (PMID 33339153, 2020). "In fact, high levels of IL-6 correlates with respiratory failure and it has become an important therapeutic target for COVID-19." (PMID 32766251, 2020). "We also observed moderate correlations of D-dimer with NLR, IL-6 levels, and CT imaging of the lungs in COVID-19-infected patients." (PMID 33195321, 2020). "In the USA, FDA declared the emergency use authorization for use of IL-6 immunoassay for COVID-19 patients." (PMID 33024459, 2020). "Together with PI3Kδ inhibitor Idelalisib, Ebastine treatment in COVID-19 also appears to be an excellent inhibitory drug approach to T-cell pro-inflammatory cytokines IL-6 and TNF-α as demonstrated in allergic diseases." (PMID 32973818, 2020). "Some COVID-19 patients typically show increased IL-6 and C-reactive protein levels before death, indicative of the progress of inflammation in the COVID-19 heart." (PMID 33232272, 2020). "These complications occurred when IL-6 peaked at a high plasma concentration late during the course of COVID-19." (PMID 33339534, 2020). "The pathogenesis of COVID-19 involves a potent inflammatory response, involving a complex group of mediators including IL-6 and IL-10." (PMID 32475230, 2020). "The National Health Commission of China has also suggested the use of tocilizumab in patients with COVID-19 with extensive bilateral lung lesions opacity or in critically ill patients with increased IL-6 levels." (PMID 32782493, 2020). "IL-6, for example, is elevated in obese COVID-19 patients and has been suggested to be a key proinflammatory factor that triggers the inflammatory storm." (PMID 33267871, 2020). "NF-κB controls the expression of many pro-inflammatory cytokines, including IL-1β, TNF-α, IL8, IL-6, all of which are induced in the cytokines storm syndrome and in COVID-19." (PMID 32708322, 2020). "For instance, in plasma of COVID-19 patients, high concentrations of IL-2, IL-6, and IL-7 were observed." (PMID 33206688, 2020). "In this study, the authors suggest that IL-6 dosage should be performed to all patients diagnosed with COVID-19 and that the existing scoring system should be customized using IL-6 concentrations." (PMID 32546188, 2020). "In patients diagnosed with severe COVID-19, increased levels of pro-inflammatory cytokines, in particular the soluble interleukin 2 receptor (IL-2R), interleukin-6 (IL-6), and tumor necrosis factor-α (TNF-α), have been observed." (PMID 32546188, 2020). "The increase of serum IL-6, decrease of lymphocytes, and increase of neutrophils were also noticed in patients over 60 years old, which help us understand why COVID-19 is more dangerous for the elder population." (PMID 33329518, 2020). "The IL-6 plays a crucial role in the pathologic of COVID-19, including the chemotaxis of neutrophils and lymphocyte necrosis." (PMID 32754163, 2020). "Laboratory biomarkers reportedly associated with COVID-19 pathophysiology include lymphocytes, CRP, D-dimer, PCT, troponins, ferritin, and IL-6, among others." (PMID 32727345, 2020).
COVID-19 (continued). "Sleep deprivation as well as loneliness have also been demonstrated to alter immune cell IL-6 production, further strengthening the evidence that individual-level adversity alters immune cell function and hence could predispose an individual to greater risk for increasing COVID-19 severity." (PMID 33134238, 2020). "IL-6 is one of the important cytokines released by inflammatory cells, especially macrophage, and is increased in COVID-19 patients at severe-to-critical stages." (PMID 32760915, 2020). "Among the more than 20 inflammatory mediators elevated in severe/critically ill COVID-19 patients, IL-6 is a prime target for intervention." (PMID 32766256, 2020). "Multiple studies have revealed elevated levels of cytokines, including IL-6, in patients with severe COVID-19." (PMID 32629804, 2020). "A more recent study on COVID-19 indicates a high-level expression of IL-6 in the blood with an average of 7 and 12 ng/ml detected in discharged and expired patients, respectively." (PMID 34192260, 2020). "Our findings suggest that distinct levels of cytokine production are associated with CRS induced by bacterial infection and COVID-19, but both CRS types are accompanied by endotheliopathy through IL-6 trans-signaling." (PMID 32826331, 2020). "Since early clinical experiences with these IL-6 inhibitors were sufficiently positive, tocilizumab and sarilumab are both being studied in vitro for treatment of COVID-19." (PMID 32629804, 2020). "Based on the clinical cytokine profile across the studies in critical/deceased patients, serum IL-6 level is well established as a reliable predictive marker for COVID-19 severity and a potential marker of ARDS along with increased neutrophil/lymphocyte ratio." (PMID 33335518, 2020). "In COVID-19 patients, an increase in many cytokines has been found, including IL-6 and IL-8, especially in severe cases." (PMID 32724296, 2020). "A recent study also suggested elevated levels of IL-6 and its soluble receptor in COVID-19 patients." (PMID 33284859, 2020). "In contrast to glucocorticoids, TCZ, a recombinant human IL-6 monoclonal antibody, showed potential therapeutic value for COVID-19 patients." (PMID 32733921, 2020). "It was widely used because it inhibits the production and release of TNF and IL-6, which has useful effects in COVID-19 patients." (PMID 32967358, 2020). "The efficacy of blocking IL-6 signaling in COVID-19 is currently under investigation, with still unexplored backstage." (PMID 32636755, 2020). "While serum IL-6 become obviously elevated in severe COVID-19 patients, serum IL-8 was easily detectible in COVID-19 patients with mild syndromes." (PMID 33488599, 2020). "Multivariate COX regression analysis showed that serum levels of IL-6 and glucocorticoid treatment were independent and protective factors, respectively, for the prognosis of severe COVID-19 patients with coexisting comorbidities." (PMID 33232277, 2020). "For instance, serum amyloid-A acts directly on macrophages, facilitating the increase in inflammatory cytokines secretion, including IL-6, which is an important component of the cytokine storm; commonly observed in severely ill COVID-19 patients." (PMID 33396584, 2020). "Currently, scientists have proposed utilizing IL-6 blockade to manage COVID-19-induced cytokine release syndrome." (PMID 32522278, 2020). "To investigate how D-dimer contributes to the disease progression of a COVID-19 infection, we observed that the D-dimer level exhibited moderate correlations with NLR (R = 0.5195, p < 0.001) and IL-6 (R = 0.543, p < 0.0001) in COVID-19 infected patients." (PMID 33195321, 2020). "In this context, antibodies against the proinflammatory cytokine IL-6 (e.g., tocilizumab) are currently under intense investigation for use in COVID-19 patients." (PMID 33207589, 2020). "In the blood of the patients with severe symptoms of COVID-19, very large quantities of IL6 are detected, a marker of the inflammatory state." (PMID 32580440, 2020).